AFP (alpha fetoprotein)
Diseases named in the same sentence as AFP in open-access papers (continued):
Sharing a sentence is not in itself a finding about the gene and the disease.
tumor (continued). "Ultimately, the presence of MetS (p = 0.026), AFP >400 ng/ml (p = 0.008), tumor size (p = 0.012), multiple nodules (p = 0.012), MVI (p = 0.030), and CCI (p = 0.030) were considered to be independent risk factors for OS." (PMID 35356224, 2022). "This success has led to the expansion of the Milan Criteria, which solely relies on the primary tumor size and number of nodules to determine whether a patient with HCC is eligible for LT and to also include other criteria, such as alpha-fetoprotein levels." (PMID 35159010, 2022). "Moreover, we note that tumor marker cut-off values differed between SIOP (HCG >50 IU/L, AFP 25 ng/mL) and COG (HCG >100 IU/L, AFP 10 ng/mL) clinical trials, which led to differences in the patients that were registered as NGGCT cases in these trials." (PMID 36132131, 2022). "In order to study new tumor treatment methods, such as the use of checkpoint inhibitors for immunotherapy except for AFP, new biomarkers have not yet entered daily practice." (PMID 36462500, 2022). "The results showed that tumor size > 5 cm, microscopic vascular invasion, macroscopic vascular invasion, and tumor multiplicity were also independent poor prognostic factors for AFP-positive HCC patients regarding DFS but not OS." (PMID 35059044, 2022). "Our research and previous studies have found that patients achieving an early AFP response have a significantly better tumor response compared with non-responders." (PMID 35251977, 2022). "HAS is a kind of tumor located in the stomach and typical of hepatoid differentiation with or without the secretion of AFP, which has a strong ability of invasion and metastasis." (PMID 36010842, 2022). "Some factors in the TME could modify the function of tumor-infiltrating DCs, such as the liver X receptor (LXR), IL-37 and alpha-fetoprotein (AFP)." (PMID 35619702, 2022). "The results indicated that AFP expressions and glycogen distributions were similar in parent tumor tissue and HCC PDOs with or without lactate supplementation." (PMID 35443744, 2022). "In our study, some of the clinico-radiological factors, such as tumor margin, peritumoral enhancement, intratumor necrosis, microvascular invasion, and AFP, were not significantly correlated with ER of HCC in multivariable Cox regression analysis." (PMID 36213823, 2022). "Among these markers, CEA, CA199, and CYFRA21‐1 levels significantly increased with the increase in tumor size (p < 0.05), whereas AFP, CA724, and NSE showed no significant differential expression levels in patients with different tumor sizes (p >0.05)." (PMID 35289087, 2022). "On the 45th day after OLT, the patient's alpha fetoprotein (AFP) and lens culinaris agglutinin-reactive fraction of AFP (AFP-L3) were increased, and imaging examination showed no residual tumor." (PMID 36119543, 2022). "AFP ≥ 400 ng mL−1, tumor size (maximum diameter >7 cm), increase in ALBI score, no tumor response, and increase in AST ≥25% are each assigned a score of 1 (total score range of 0–5)." (PMID 35884412, 2022). "Abdominal CT showed no tumor recurrence one month post-operation, whereas the AFP level gradually returned to normal within six months after surgery." (PMID 36551543, 2022). "Several blood tumor markers, AFP and DCP, and liver condition markers, ALBI score and FIB-4 index, were also significantly increased in the Deceased group compared to the Survival group (AFP and DCP; P < 0.0001, ALBI score and FIB-4 index; P < 0.01)." (PMID 36081568, 2022). "Accordingly, the rate of vascular invasion was significantly lower (20% vs. 31%, p < 0.001) and the percentage of pathological complete tumor necrosis was significantly higher (25 % vs. 16%, p = 0.01) in AFP-negative patients." (PMID 35529597, 2022). "AFP with AFP-L3 is measured when there is a strong suspicion of HCC recurrence after tumor ablation, and in particular when a high level of AFP was noted in patients without risk for HCC." (PMID 35458505, 2022).
tumor (continued). "Serum tumor markers mainly include CA125, HE4, CEA, AFP, and CA199." (PMID 35912239, 2022). "There are factors that are prognostically important in HCC which are categorized into groups as hepatocellular-related factors (liver function tests, bilirubin) and tumor aggressiveness related factors (tumor size, presence of PVT, elevated AFP levels, and tumor multifocality)." (PMID 35411218, 2022). "In addition, high expression of PD-L1 can increase the level of AFP in the blood of HCC patients, thus, promoting tumour progression." (PMID 36291944, 2022). "The univariate and multivariate analyses revealed that tumor size (HR [95%]: 1.592[1.313–1.930], P<0.001), periportal HCC (HR [95%]: 2.417[1.559–3.745], P<0.001) and AFP ≥ 400 (HR [95%]: 2.955[1.652–5.283], P<0.001) were independent prognostic factors for tumor progression after RFA." (PMID 34983650, 2022). "AFP is the approved marker for screening HCC among serological biomarkers, while it has an insufficient sensitivity to detect early-stage HCC patients, because AFP level is correlated with the extent of tumor burden." (PMID 35751040, 2022). "The most frequently assessed tumor marker before first-line chemotherapy was the CEA level (82.9%), followed by the CYFRA (73.1%), SCC antigen (66.4%), ProGRP (58.0%), NSE (51.4%), and AFP levels (37.4%)." (PMID 35053494, 2022). "The alpha-fetoprotein(AFP) level and its longitudinal change during perioperative period in surgical resectable HCC could provide some evidence of early tumor recurrence and tumor residues." (PMID 35379737, 2022). "Those tumor markers, such as carcinoembryonic antigen (CEA), alpha-fetoprotein (AFP), and prostate specific antigen (PSA), were captured by aptamer 1 (apt1)-coated MBs and the release of signal DNA was triggered after incubation with duplexes of signal DNA and aptamer 2 (apt2)." (PMID 36004973, 2022). "Serum fCK18 levels, as well as AFP and DCP, were significantly elevated in the HCC up-to-seven group (largest tumor diameter [in cm] + tumor number > 7) (P < 0.0001), while FIB-4 index and ALBI score was the same between groups in or out of the HCC up-to-seven criteria." (PMID 36081568, 2022). "In a comparison of marker triplets, AFP-HMMR-PITX, HMMR-NXPH4-PITX1 and HMMR-PITX1-THBS4, all exhibited better AUC, sensitivity, specificity, accuracy and other values in patients with HCC or eHCC compared with non-tumor cases." (PMID 35456219, 2022). "An AFP level ≥ 400 was independently predictive of shorter PFS in our study but not of OS, but elevated AFP has been well-established as a prognostic biomarker in HCC and correlated with pathologic grade, stage, and tumor size." (PMID 36497316, 2022). "Additional initial selection criteria like AFP-DCP/PIVKA-II, PET-CT, or tumor biopsy might be of help with this specific subgroup but has yet to be fully investigated." (PMID 35529597, 2022). "In addition, the relation of IL-8 with the classic tumor biomarkers, including CEA, AFP, CA199, CA125 and CA153, was evaluated." (PMID 36185222, 2022). "sEVs derived from AFP-expressing DCs have been shown to elicit strong antigen-specific immune responses, with increased INF-γ-expressing CD8 + T cells and decreased Tregs at tumour sites." (PMID 36167539, 2022). "At relapse, 39 patients (81%) had AFP elevation, one (2%) had β-hCG elevation, seven (15%) had both tumor markers elevated and one did not have available tumor marker data." (PMID 35204369, 2022). "After univariate and multivariate regression analyses, AFP, tumor size, nonperipheral “washout”, infiltrative appearance, marked diffusion restriction, and iron sparing in solid mass were selected to construct the prediction model of this study." (PMID 36091074, 2022). "After adjusting for age, sex, smoking, operation time, lymphovascular invasion, allogeneic blood, HB, AST, ALP, HBsAg, tumor number, tumor size and AFP, a nonlinear relationship between GLR and incident recurrence was found." (PMID 35395799, 2022).
tumor (continued). "Multivariate analysis demonstrated that patients with a tumour diameter of less than 30 mm, a unifocal disease, lacking vascular infiltration and AFP serum levels within the normal range had a significantly better OS." (PMID 36233670, 2022). "Meanwhile, PRS was also not correlated with age, sex, Child-Pugh classification, AFP level, and tumor number across all three cohorts." (PMID 36324581, 2022). "In terms of tumor factors, good OS results were associated with a lower BCLC classification, no PVTT, presence of a single tumor, lower level of AFP, and intrahepatic local treatment." (PMID 35183265, 2022). "AST (HR = 2.200, p = 0.009), tumor capsule (HR = 0.392, p = 0.017), rim enhancement (HR = 2.825, p = 0.002) and TTPVI (HR = 5.511, p < 0.001) were independent predictors for early recurrence of AFP-NHCC patients." (PMID 35626229, 2022). "In addition to the raw data of tumor markers, the cutoff and ratio of tumor markers (CEA/CA19-9, CEA/CA153, CEA/CA125, CEA/AFP, CA19-9/CA153, CA19-9/CA125, CA19-9/AFP, CA153/CA125, CA153/AFP, CA125/AFP) were included in the predictive analysis." (PMID 35433129, 2022). "Univariate and multivariate analysis indicated that PVTT, the number of intrahepatic tumors, and the level of AFP were poor prognostic factors, whereas tumor size was not." (PMID 36471084, 2022). "The diagnostic AUC of LG3BP was 0.904, which was much higher than that of a non-specific tumor marker alpha-fetoprotein (AUC = 0.802)." (PMID 35757760, 2022). "We also found that the combination therapy was not beneficial in patients with M1 along with a tumor size of 2–3 cm, one recurrent tumor, or AFP ≤400 μg/L, probably because sorafenib was unable to be taken full advantage in this subpopulation." (PMID 35814378, 2022). "Especially, AFP is commonly used in clinical practice to diagnose HCC and various tumours." (PMID 36345011, 2022). "Laboratory findings showed that tumor markers (CEA, AFP, CA125 and CA199) were unremarkable." (PMID 35072798, 2022). "Some studies have indicated that serum AFP levels and non-smooth tumor margins are more frequently found in MVI-positive HCC cases." (PMID 35402463, 2022). "Univariate analysis revealed the following as significantly associated with overall survival (OS, months): mALBI grade 2b or 3, tumor node metastasis (TNM) stage, alpha fetoprotein (AFP) ≥ 56.7 ng/dL, receiving other treatments after discontinuing LEN, and severe muscle atrophy (ΔPMI/m ≥ 1%)." (PMID 35444161, 2022). "In fact, relapsed HCCs had higher AFP levels, more undifferentiated grading, and higher tumor size than non-recurrent patients." (PMID 36158651, 2022). "Cryoablation combined with multiple infusions of allogenic natural killer (NK) cells had synergistic effect on patients with HCC, reducing tumor biomarker alpha fetoprotein levels and improving median progression-free survival (PFS), tumor size reduction, and quality of life post-treatment." (PMID 35265206, 2022). "Furthermore, tumor size, vascular invasion, tumor capsule formation, satellite nodules, TNM stage, and AFP were identified as the significant variables both for disease-free and overall survival, which were in line with the previous studies." (PMID 35729607, 2022). "After demonstrated response to locoregional therapy with AFP of 5 ng/mL and no viable tumor on the next scan, this patient would then have a calculated dropout risk of 3% at 3 months, 7% at 6 months, and 15% at 12 months." (PMID 35029055, 2022). "Immunohistochemical results: CK7 foci (+), CK18 (weak + - +), CK19 (weak + - +), CK20 (−), CDX2 (weak + - +), AFP (−), Hepar1 (−), Arg-1 (−), GATA-3 (−), Vim (-), P40 a little (+), CD117 (−), CerbB2 (−), Ki-67 (+) 80%-90%, EBV in situ hybridization: tumor cells EBER (+)." (PMID 35945590, 2022).
tumor (continued). "The results revealed that AFP>10 ng/ml, tumor size>3.0 cm, nonperipheral “washout”, infiltrative appearance, marked diffusion restriction, and iron sparing in solid mass were significantly associated with GPC-3 positive expression." (PMID 36091074, 2022). "The following 12 variables related to the prognosis of HCC were considered at the start of the follow-up: age, sex, etiology, Child–Pugh class, tumor size, BCLC stage, albumin level, total bilirubin level, ALBI score, prothrombin time, AFP level, and DCP level." (PMID 35329809, 2022). "Analysis of the correlation between tumour markers and blood parameters in all groups demonstrated that the severity of BCLC staging, Child–Pugh score, total bilirubin, ALT, and INR levels were positively correlated with both PIVKA-II and AFP levels." (PMID 36013482, 2022). "Moreover, results have shown that hemoglobin negatively correlates with tumor markers CEA(r = -0.475; p = 0.001), AFP (r = -0.383; p = 0.007) and CA 19-9 (r = -0.610; p = 0.001), respectively." (PMID 35611243, 2022). "AFP and des-γ-carboxy prothrombin (DCP) are tumor markers for HCC." (PMID 35020772, 2022). "Therefore, we combined histopathological images and tumor-specific biomarkers, including CEA, CA125, CA19-9, and AFP through deep learning to develop an automatically predictive model." (PMID 37850180, 2022). "AFP and CA19-9 may influence the tumor biological characteristics of HCC through different mechanisms, with similar consequences for prognosis." (PMID 36258212, 2022). "Third, all patients with AFP-NHCC underwent surgical resection in our study, whether the predictive nomogram would be suitable for patients who received other anti-tumor treatments remains uncertain." (PMID 35626229, 2022). "B-HCG and alpha-fetoprotein (AFP) tumor markers are usually not elevated in the case of paratesticular RMS." (PMID 36550579, 2022). "For the LT candidate, they recommended that it is better to monitor the progress of the T1 tumor without BT, but once the AFP is elevated to ≥500 ng/mL or the tumor is growing in a short period of time, locoregional therapy should be given as soon as possible." (PMID 35053558, 2022). "Among all patients, half exhibited stable disease (SD), one had decreased tumor size (from 13 mm to 7 mm in diameter), and another had lowered serum levels of HCC tumor markers such as alpha-fetoprotein (AFP) and protein induced by vitamin K absence or antagonist II (PIVKA-II) after vaccination." (PMID 36139542, 2022). "Performance status (PS) score, major tumor diameter, white blood cell (WBC) count, alpha-fetoprotein (AFP) level, location of pathological changes, Child–Pugh class, and the number of intrahepatic pathological changes were significantly different among the three groups of patients, (P < 0.05)." (PMID 35710505, 2022). "We found that people developed VER tend to have these clinical factors: the performance of major resection, lymph node dissection, tumor size> = 5 cm, the presence of MiVI, MaVI, and SN, GGT> = 75 U/L, ALP > = 78 U/L, AFP > = 20 ng/mL, CA19-9 > = 25 U/mL, and DCP > = 200 mAU/mL." (PMID 35227269, 2022). "DLK1 presence did not correlate with other classic prognostic factors such as AFP, tumor node metastasis, or vascular invasion." (PMID 35805898, 2022). "Group 2 comprised patients who did not meet the “Up-to-seven” criteria or those with AFP of > 1000 ng/mL, and they had larger tumor sizes and higher AFP levels than group 1." (PMID 35936699, 2022). "Zhang found that LPCAT1 expression was related to tumor grade, ECOG score, AFP and TNM stage." (PMID 36307879, 2022). "Multivariate Cox regression and RF models before and after PSM analysis revealed that the main prognostic factors affecting survival were tumor number, portal vein tumor thrombus (PVTT) invasion, alpha-fetoprotein (AFP) levels, total bilirubin (TBIL) level, and treatment." (PMID 36249011, 2022).
tumor (continued). "GA with AFP-producing and GAPEP were rare tumor, and the quantity of those cases was limited." (PMID 34706681, 2021). "ROC analysis showed a good performance of the model in patients with single nodule, absent macrovascular invasion, and small tumor size < 2 cm (AUC of 0.95, 0.94, and 0.95, respectively), compared to AFP (AUC of 0.71, 0.74, and 0.72, respectively)." (PMID 34714420, 2021). "For Model II, absence of CEUS LR-5 (OR=4.37), 20 ng/mL<AFP level<400 ng/mL (OR=3.27) and tumor size larger than 30 mm (OR=3.74) were significant factors for predicting MVI while AFP levels higher than 400 ng/mL were not." (PMID 34307168, 2021). "However, patients with AFP-NHCC have special clinicopathologic characteristics and prognosis, they have higher tumor differentiation, earlier TNM staging, smaller tumor size, and higher survival rates." (PMID 33685417, 2021). "NLR alone gave an AUROC of 0.728 (p-value = 0.043), higher than AFP, CEA or tumor size alone." (PMID 34834430, 2021). "Tumor markers, including CEA, CA125, CA199, AFP and serological investigations for connective tissue disease, such as anti-nuclear antibodies, anti-dsDNA antibody, anti-neutrophil cytoplasmic antibody, rheumatoid factor and immunoglobulin (IgA, IgG, IgM) were all negative." (PMID 34629105, 2021). "After stepwise removal of the variables which were not significant, maximum tumor size, tumor number, extension of mPVTT, and AFP remained as significant predictors of OS that will be considered for further model development." (PMID 34513667, 2021). "There was no statistical difference for the maximum tumor diameter, number of tumors, serum α-fetoprotein (AFP) value, and Des-Gamma-Carboxy prothrombin (DCP) value between the two groups." (PMID 34831479, 2021). "AFP and GPC3, which are known tumor markers for HCC, were classified as A genes." (PMID 33539378, 2021). "In comparison to the performance of single tumor markers, two-marker combinations of CEA plus AFP (CEA+AFP) and CEA plus CA19-9 (CEA+CA19-9) showed similar sensitivities to those of CEA alone for detecting all-stage CRCs, but much higher than those of AFP+CA19-9 combination." (PMID 33977101, 2021). "Univariate analysis demonstrated that AJCC stage, tumor size, grade, surgery and radiotherapy were associated with OS in the non-chemotherapy group, and AJCC stage, tumor size, AFP, fibrosis score, grade, surgery and radiotherapy in the chemotherapy group." (PMID 34887446, 2021). "In addition, plasma alpha-fetoprotein (AFP) levels, a common tumor marker for HCC, remain within the normal range in 15–30% of advanced HCC patients." (PMID 34535132, 2021). "In addition, univariate Cox regression analysis showed that tumor size, differentiation degree, T stage, N stage, TNM stage, AFP overexpression, Ki67 expression, and EWSR1 overexpression were each significantly associated with OS (P < 0.05)." (PMID 34612781, 2021). "After excluding non-surgical patients, univariate analysis showed that the tumor size, pathological grade, TNM stage, T stage, N stage, M stage, AFP status, and chemotherapy were risk factors of prognosis (P<0.1)." (PMID 34336671, 2021). "PIVKA-II binds to the hepatocyte growth factor receptor, c-MET, leading to tumour growth, invasion and tumour metastases via the JAK-1/STAT3 and ERK 1/2 MAPK signalling pathways, whereas AFP is thought to be more a marker for hepatic progenitor cells or their subtypes." (PMID 34853657, 2021). "The commonly used blood biochemical markers are total bilirubin, aspartate aminotransferase (ASAT), alanine aminotransferase (ALAT), and tumor markers such as cancer-related antigen 72.4 (CA72.4), carcinoembryonic antigen (CEA), carbohydrate 19-9 (CA19-9), and alpha-fetoprotein (AFP), among others." (PMID 35008366, 2021).